IL6 (interleukin 6)
Diseases named in the same sentence as IL6 in open-access papers (continued):
Sharing a sentence is not in itself a finding about the gene and the disease.
breast cancer (continued). "Metastasizing cancer cells stimulated myeloid-derived suppressor cells to secrete elevated levels of IL-6 and IL-6 receptor-α, which in turn stimulated breast cancer cell aggressiveness and metastasis." (PMID 33809315, 2021). "Serum IL-8, along with IL-6, was reported as significantly decreased in radiotherapy responder breast cancer patients when compared to baseline levels." (PMID 34830880, 2021). "miR-145 is associated with IL-6/STAT3 pathways and is under-expressed in breast cancer with high metastatic capability." (PMID 34299605, 2021). "CDKs are widely expressed in breast cancer cells and play a crucial role in the initiation of an inflammatory cascade comprising IL-8, IL-6, VEGF-A, and others." (PMID 33732735, 2021). "In breast cancer, IL-6 activates deubiquitinase 3 (Dub3), leading to Snail, Slug and Twist1 protein stabilization, and it has been shown to stabilize the Twist protein levels through the activation of casein kinase 2 (CK2) in HNSCC." (PMID 34361105, 2021). "Although we found that 10 μg/mL of ME triggered only a slight decrease in the cell viability of breast cancer cells, this dose of ME significantly affects IL-1β and IL-6 mRNA expression." (PMID 34201348, 2021). "FABP4 supplementation increases tumor volume, tumor-initiating frequency and stemness markers, as shown in in vivo and in vitro studies on mammary tumors, depending on the IL-6/STAT3/ALDH1 signaling pathway." (PMID 34202411, 2021). "Other studies on the interaction between breast cancer and adipocytes have revealed that the inflammatory factor IL-6 is the other key player in maintaining cancer stemness." (PMID 34202411, 2021). "Annexin A2 from breast cancer exosomes can stimulate the secretion of IL-6 and TNF-α by inducing macrophage-mediated p38 MAPKs." (PMID 34485600, 2021). "IL-6 and TNFα are both important molecules for this process, and the role of NFκB-dependent PD-L1 is under intensive research in breast cancer." (PMID 34299224, 2021). "Vice versa, mesenchymal derived cells can induce STAT-3 signaling in breast cancer cell lines via IL-6, thereby enhancing breast cancer cell growth in vitro and in vivo." (PMID 33809315, 2021). "IL-6, ADA and PAI secreted by MCF7 cells in the PDS-model were significantly associated to high grade breast cancer subtypes." (PMID 34090457, 2021). "CD44 is commonly used to identify cancer stem cells and exposure to IL-6 (50 ng/mL for 10 days) enriched the CD44+ cell population in the human T47D breast cancer cell line." (PMID 33809315, 2021). "For the upstream, reactive oxygen species (ROS) and IL-6 triggered STAT3 activation regulates MDSCs expansion in the breast cancer, which are both typical characteristics of MDSCs." (PMID 33957948, 2021). "An inverse relationship has been reported between let-7 miRNA and IL-6 expression in breast cancer tissues, suggesting the importance of inflammatory activation of miRNAs-related to IL-6 pathways and regulatory circuits in stemness." (PMID 34299605, 2021). "Our study illustrates that overexpression of BQ can modulate tamoxifen resistance by enhancing the expression of IL-6 and IL-6R in ER+ breast cancer." (PMID 33806019, 2021). "OSM can also activate STAT3 and hypoxia-inducible factor-1 alpha (HIF-1α) in estrogen receptor (E.R.)- breast cancer cells or in ER + breast cancer cells in concert with IL-6." (PMID 34488773, 2021). "Increased expression and secretion of TNFα and IL-6 as seen in our study is in line with other reports where breast cancer-EVs were shown to increase these cytokines." (PMID 34203762, 2021). "Triple-negative breast cancer cells withenhanced MCTS1 expression secrete significantly more of thepro-inflammatory cytokines IL-6, MCP-1, and GM-CSF than cells with a relativelylower MCTS1 expression level." (PMID 34377560, 2021). "In breast cancer, in vitro stimulation with IL-6 increases tumor mammospheres and CD44+/CD24+ breast CSCs." (PMID 33613850, 2021).
breast cancer (continued). "In breast cancer, in vitro stimulation with IL-6 results in an increase in the number of tumor mammospheres and CD44+/CD24+ breast CSCs." (PMID 33613850, 2021). "IL-6 expressing breast cancer cells have also been shown to recruit myeloid-derived suppressor cells to infiltrate sites of primary as well as distant, metastatic tumor growth." (PMID 33809315, 2021). "Several studies have shown that chemotherapy can activate toll-like receptors 4 (TLR4), which exhibited an increase in proinflammatory IL-6 cytokine in blood and organs distant from the primary tumor in animal models and breast cancer patients." (PMID 34572719, 2021). "IL-6 is a potent cancer cell growth factor that can induce an epithelial–mesenchymal transition phenotype in breast cancer and therapeutic resistance in breast cancer." (PMID 34379689, 2021). "In HER2-positive breast cancers, IL-6 expression can induce CSC-positive phenotype through activating NF-κB and STAT3 pathways, thus driving tumorigenesis and promoting chemotherapy resistance." (PMID 34095111, 2021). "IL-6 is an important cytokine that regulates macrophage infiltration and differentiation; it can also promote breast cancer metastasis by enhancing epithelial–mesenchymal transition." (PMID 34639006, 2021). "Accordingly, the blockade of IL-6 by neutralizing antibody suppressed breast cancer progression is induced following RB1 inactivation." (PMID 34359636, 2021). "Another research group reported that circulating exosomes secreted by breast cancer cells increased macrophage NF-κB activation and induced proinflammatory activity by upregulation of inflammatory cytokines IL-6, TNFα, GCSF, and CCL2." (PMID 34207035, 2021). "Another prominent IL involved in breast cancer stemness includes IL-6, probably the most studied one, and several studies report a link between IL-6 signaling and CSCs." (PMID 33809315, 2021). "Trib3 is induced by IL6 in breast cancer cells, promotes the malignant behavior of ovarian cancer cells through Mek-Erk signaling, and induce cell migration, invasion, and metastasis of liver cancer cells." (PMID 35126382, 2021). "In studies on breast cancer patients, for example, we recently showed that increases in urinary IL-6 concentrations preceded fatigue decreases by 48–60 h and that increased levels of urinary neopterin preceded fatigue increases by 24 h and 60–72 h." (PMID 34975831, 2021). "Curtis TCGA data mining inversely correlated expression levels of oncostatin M (OSM), IL-6, and IL-1β with breast cancer patient survival." (PMID 35008370, 2021). "It has recently been shown, for example, that microbially driven TLR5-dependent IL-6 signaling promotes breast cancer malignant progression through tumor-promoting inflammation." (PMID 34359821, 2021). "Recent studies suggested that increased expression and secretion of IL-6 in CAAs plays a key role in mediating breast cancer progression." (PMID 34095111, 2021). "Low levels of butyrate have been observed in patients with breast cancer, together with elevated levels of the pro-inflammatory cytokine IL-6, which can lead to cancer development and progression." (PMID 34201776, 2021). "Along similar lines, our results showed that miR-139-mediated CXCR4 reduction correlated with decreased levels of VEGF and IL-6 in the xenograft-transplantation model of human breast cancer." (PMID 34070538, 2021). "Inflammatory cytokines are secreted during chronic inflammation, and numerous studies have indicated that serum interleukin (IL)-6 levels are greater in breast cancer patients than in healthy controls." (PMID 33962395, 2021). "Consistently, global gene expression analysis revealed that an IL-6 gene expression signature induced by the interaction of osteoblasts and breast cancer cells correlates with a shorter time to the development of bone metastasis in vivo." (PMID 33809315, 2021).
breast cancer (continued). "PIM1 promotes cell invasion, epithelial to mesenchymal transition process, and cancer cell stemness in IL-6-treated breast cancer cells." (PMID 34519263, 2021). "Further studies have also suggested the potential of IL-6/CSC-targeted therapies in patients who developed resistance to hormone therapy in luminal breast cancer." (PMID 33809315, 2021). "VEGF, TNF-α, IL-1β, and IL-6 expression levels documented in breast cancer patients were increased in the biopsies tissues compared to normal tissues." (PMID 34572719, 2021). "It has been reported that S100A9 probably plays a key role in inflammation-related breast cancers and induces the expression of pro-inflammatory cytokines (IL-6, IL-8, and IL-1β), thus, its expression level can be used to diagnose breast cancer." (PMID 34490085, 2021). "Nevertheless, in breast cancer, elevated systemic IL-6 seems to reflect poor prognosis, advanced disease and distant metastasis." (PMID 34445170, 2021). "In a mammary tumor model, increased production of Il-6 was shown to be responsible for myeloid cell recruitment to tumor microenvironment." (PMID 34868988, 2021). "In osteoblasts, Notch activation by tumor-derived Jagged1 increased Interleukin-6, which supported the survival of metastatic breast cancer cells." (PMID 34680255, 2021). "The results from the co-culture experiments suggest that RORα inhibits macrophage accumulation in breast cancer tissue at least partially through IL-6 repression." (PMID 34639006, 2021). "Most studies have focused on the role of IL-6 in invasion, migration, and hereby the metastasis of breast cancer cells." (PMID 34944905, 2021). "The mRNA expression of resistin (3.5-fold) and IL-6 (15-fold) in PBMCs of breast cancer patients significantly increased in comparison to healthy controls." (PMID 33517609, 2021). "Some years ago, others have also postulated a role of syndecan-1 in the β-integrin-, and IL-6 dependent adhesion and migration of breast cancer cells." (PMID 33809315, 2021). "A better understanding of IL-6/IL-6 R regulation and signaling needs to be taken into account to improve IL-6-based therapies in breast cancers." (PMID 34445170, 2021). "More recently, tissue array analysis of 448 cancer samples from multiple organs revealed positive correlations between Zeb1 and IL-6 protein levels in various cancer types, including liver, colon and breast cancer." (PMID 34361105, 2021). "In a murine breast cancer model, a novel cryo-thermal treatment produced an IL-6 driven acute phase protein cluster predominating in the first 48 h, followed in subsequent weeks by tumour progression-associated proteins." (PMID 34885149, 2021). "The adipocytes released leptin and IL-6 to promote metastasis in breast cancer cells by upregulating PLOD 2 expression via JAK/STAT and PI3K/AkT signaling." (PMID 34588926, 2021). "One study found that high levels of IL-6 in the circulation are a sign of poor prognosis in breast cancer, melanoma, and myeloma." (PMID 34801005, 2021). "Breast cancer patients present an increase in pro-inflammatory cytokines (IL-1β, IL-6, IL-18, TNFα and IFNγ)." (PMID 34201776, 2021). "Together with our previous study, we therefore identified a novel molecular pathway to modulate IL-6 expression in ER+ breast cancer." (PMID 33806019, 2021). "CD44+ T47D breast cancer stem cells induced by IL-6 have been shown to undergo EMT in vitro, which was characterized by an increased presence of vimentin." (PMID 33809315, 2021). "In the context of cancer, blockade of IL‐6 has been shown to reduce prostate cancer and breast cancer–induced bone destruction." (PMID 33869989, 2021). "have shown that NOTCH3 is involved in regulation of IL6-mediated hormone therapy resistance in breast cancer." (PMID 34374886, 2021).
breast cancer (continued). "In accordance with this finding, previous clinical studies had shown that the elevated serum concentrations of IL-6 and IL-8 of breast cancer patients correlate with the stage of the disease, the recurrence, and are indicators of poor prognosis." (PMID 34445170, 2021). "13R,20-diHDHA deregulates this equilibrium through dephosphorylation of Stat3 and deregulation of IL-6, and thereby reduces the cancer stemness of breast cancer cells." (PMID 33804152, 2021). "When adipocytes are co-cultured with breast cancer cells, cytokines are secreted, specifically IL-8, IL-6, IFNγ-inducible protein 10, CCL2, and CCL5." (PMID 34912237, 2021). "Isolated fibroblasts from common sites of breast cancer metastasis, including lung and bone, produce elevated levels of IL-6 when compared to normal skin fibroblasts." (PMID 33809315, 2021). "On the other hand, osteoblasts have been shown to express increased levels of inflammatory cytokines including IL-6 and IL-8 upon the presence of breast cancer cells, which facilitates metastatic breast cancer growth in bone." (PMID 33809315, 2021). "Activated human T cells are involved in the synthesis of IL-6, TNFα, and TGFβ which induce the expression of mesenchymal proteins such as fibronectin, vimentin, and Zeb1 in inflammatory breast cancer cells." (PMID 34220337, 2021). "In breast cancer cells, activation of STAT3 via the IL-6/JAK2 cascade causes suppression of Bax/Bcl-2-associated caspase-dependent apoptosis." (PMID 34488773, 2021). "Existing studies indicate that IL-6 can stimulate EMT in cancer cells like cervical carcinoma or breast cancer." (PMID 35127527, 2021). "Accordingly, exposure of breast cancer cells to recombinant IL-6 or IL-8 enhances their migration and invasion properties, as well as induces mammosphere formation, a readout for CSC potential." (PMID 34621683, 2021). "IL-6, IL-8, CCL2, and CCL5 have been found to be stimulators of the proliferation, survival, and invasion of breast cancer cells and are linked to an advanced stage of breast cancer." (PMID 34912237, 2021). "Using breast cancer spheroids, it has been shown that IL6 secreted by fibroblasts present in the tumor microenvironment induces the synthesis of hepcidin in breast cancer cells, which in turn leads to FPN degradation." (PMID 33804198, 2021). "A more specific study on the gene expression of biomarkers in breast cancer revealed that the expression levels of IL-6, TNF-α, and leptin were higher in the breast adipose tissues of women with high waist circumference." (PMID 35008370, 2021). "Separate studies investigating the osteoblast-breast cancer interaction during breast cancer bone metastasis showed that osteoblasts increase IL-6 in breast cancer cells via RANKL, resulting in a positive feedback loop." (PMID 33809315, 2021). "In HER2-positive breast cancer, IL-6 enhances breast cancer progression through expansion of the cancer stem cell population." (PMID 34944905, 2021). "In a pilot study of 16 breast cancer patients, TNFa, IL-6 and TGFb production by peripheral blood T cells was correlated with the detection of circulating tumor cells expressing EMT markers." (PMID 34885027, 2021). "Various clinical studies have correlated high circulating IL-6 levels in patients with malignant tumors, as for breast cancer, prostate cancer, head and neck squamous cell carcinoma or renal cancer." (PMID 34445170, 2021). "MK-0752 (25 μM) and RO4929097(10 μM), alone or in combination with tocilizumab, suppressed tumor growth, but enhanced the CSCs in breast cancer cells expressing Notch3, while inducing IL-6." (PMID 33673088, 2021). "Scholars discovered the GPX8/IL-6/STAT3 axis as an essential pathway in regulating cell aggressiveness of breast cancer." (PMID 34284774, 2021). "The recent study reported that anti-PD-L1 treatment or the Rhein plus PD-L1 therapy groups upregulated the IL6 level in the established 4T1 breast cancer xenografts." (PMID 34479503, 2021).
breast cancer (continued). "A similar differential effect was also evident for the inflammatory mediators IL-6 and IL-8, which were suppressed in ER- but induced in ER+ breast cancer cells." (PMID 35111687, 2021). "IL-6 was shown to trigger spheroid formation in the MCF-7 breast cancer cell line, thus indicating that its pro-inflammatory loop mediates enrichment in mammary stem cells." (PMID 34638901, 2021). "Osteoblasts produce increased levels of inflammatory cytokines (e.g., IL-6 and IL-8) upon stimulation with breast cancer cells." (PMID 33809315, 2021). "In another study, the frequency of the CD44+/CD24- population—marking breast cancer stem cells (CSCs)—was diminished, and the expression and activation of the pro-inflammatory IL-6/STAT3 pathway reduced after Sdc-1 siRNA knockdown." (PMID 34070901, 2021). "All these findings suggest that immunity levels (characterized by a reduced IL-6 level and intact DC maturation in Fvb.B6 mice) are the key factors affecting tumor onset in a murine mammary cancer model." (PMID 33568170, 2021). "An important regulator of EMT in breast cancer cells is the chemokine IL6, which is strongly expressed in adipocytes and therefore highly abundant in mammary tissue." (PMID 34207792, 2021). "TGFβ1 induces overexpression of IL-6 in TAMs and T cells which are involved in the poor survival of breast cancer." (PMID 34220337, 2021). "Nevertheless, high FRH (41 °C) decreases the IL-1β mRNA level, and it surprisingly increases the level of IL-6 mRNA in ME-treated 4T1 breast cancer cells." (PMID 34201348, 2021). "Here, we review and discuss the role of the best-validated ILs (IL-1β, IL-6, IL-8 and IL-11) involved in the bone cell—breast cancer cell crosstalk during the early events of breast cancer bone metastasis." (PMID 33809315, 2021). "Earlier, we reported that the levels of resistin and IL-6 were significantly more elevated in the serum of African American women with breast cancer than in their Caucasian American counterparts." (PMID 34572725, 2021). "In Siltuximab-treated ovarian cancer and ERα-positive breast cancer, cancer cells were found to reduce IL-6 production, which inhibited tumor growth, TAMs invasion and angiogenesis." (PMID 34717710, 2021). "Transcriptional factor C/EBP was activated through the IL-6 autocrine loop mechanism, causing MDR-1 upregulation and inducing resistance to doxorubicin, vincristine, and taxol in IL-6-expressing mammary carcinoma cells." (PMID 34226586, 2021). "Propofol epigenetically regulates trastuzumab resistance in breast carcinoma through intervening interleukin-6/miR-149-5p axis." (PMID 34775376, 2021). "Highly enriched of glycoprotein 130 (gp130) from breast cancer (BC)-derived exosomes triggers the secretion of interleukin-6 (IL-6) and activate the IL-6/STAT3 pathway." (PMID 34722637, 2021). "IL-6 is one of the signaling molecules that contributes to chemotherapy resistance in breast cancer." (PMID 32806551, 2020). "We found increased mRNA expression of Il17f, and a tendency toward an increase of Il17c and Il6, in the mammary tumors of HFD offspring." (PMID 32580156, 2020). "Subsequently, Jagged1-mediated Notch signaling pathway promoted IL-4 and IL-6 secretions in breast cancer cells and ultimately inducing M2 polarization of macrophages." (PMID 32943090, 2020). "Faecalibacterium prausnitzii also suppressed the proliferation and invasion and promoted the apoptosis of breast cancer cells, while these effects disappeared after adding recombinant human IL-6." (PMID 32272885, 2020). "Faecalibacterium prausnitzii suppresses the growth of breast cancer cells through inhibition of IL-6/STAT3 pathway." (PMID 32272885, 2020). "IL-6 facilitates osteosarcoma and liver tumor progression, while it inhibits lung and breast cancer development." (PMID 32134471, 2020). "IL-6 seems to be an important cytokine in breast cancer studies acting in several pathways involved in cancer progression." (PMID 32411334, 2020).